DHRS13 (dehydrogenase/reductase 13)
Description:
Putative oxidoreductase.
Synonyms: SDR7C5; MGC23280
Tractability: Antibody: UniProt places it where antibodies can reach, with high confidence; UniProt predicts a signal peptide or a membrane-spanning region; its Gene Ontology location is reachable by antibodies, with medium confidence. PROTAC: ubiquitination databases record sites on it; its protein half-life has been measured.
Gene: Protein-coding gene on chromosome 17 (28,897,781 to 28,903,079, reverse strand). Ensembl gene ENSG00000167536.
Subcellular location: Secreted
Subcellular location (Human Protein Atlas): Vesicles; Predicted to be secreted
Gene Ontology:
Molecular function: protein binding; oxidoreductase activity
Cellular component: membrane; extracellular region
Genetic constraint (gnomAD): Loss-of-function variants: 28 observed, 18.94 expected, observed/expected ratio (o/e) 1.48, 90% interval 1.09 to 1.89. The upper end of that interval is the gene's LOEUF score, 1.89, which puts it in group 6 of 6, group 1 being the genes least tolerant of losing a copy. Missense variants: 483 observed, 476.57 expected, observed/expected ratio (o/e) 1.01, 90% interval 0.94 to 1.09. Synonymous variants: 206 observed, 198.52 expected, observed/expected ratio (o/e) 1.04, 90% interval 0.93 to 1.16.
Homologues: Orthologues: chimpanzee DHRS13 (100% identical), macaque DHRS13 (97% identical), pig DHRS13 (90% identical), rabbit DHRS13 (86% identical), guinea pig DHRS13 (85% identical), mouse Dhrs13 (84% identical), rat Dhrs13 (83% identical), dog DHRS13 (71% identical), tropical clawed frog dhrs13 (47% identical), zebrafish dhrs13a.3 (45% identical), zebrafish dhrs13a.1 (42% identical), zebrafish dhrs13b.1 (42% identical), and 8 more. Paralogues in human: RDH13 (37% identical), RDH14 (36% identical), DHRSX (25% identical), KDSR (20% identical).
Diseases named in the same sentence as DHRS13 in open-access papers:
DHRS13 is named in the same sentence as 3 diseases in open-access papers, as found by Europe PMC text mining. Sharing a sentence is not in itself a finding about the gene and the disease. The quoted sentences say what the papers report.
breast carcinoma (1 paper, 2022). "Finally, DHRS13, ERAL1, and SLC9A3R2 could predict treatment response and survival; however, there are no reports related to breast cancer and its possible function in this disease." (PMID 36338974, 2022).
tumor (1 paper, 2022). "In the HPA data, compared with normal tissues, DHRS13, PLEKHH1were expressed at medium to high levels in tumor tissues, while the expression of PSMB9, and LRRN2 was significantly up-regulated in OC samples, and AMMECR1, KIAA0100 slightly downregulated in OC samples." (PMID 36307842, 2022).
DHRS13 also shares sentences with these, for which no sentence is quoted: geographic atrophy (1 paper).